ENSG00000268643 (novel protein)
Gene: Protein-coding gene on chromosome 19 (42,234,583 to 42,255,132, reverse strand). Ensembl gene ENSG00000268643.
Genetic constraint (gnomAD): Loss-of-function variants: 2 observed, 13.06 expected, observed/expected ratio (o/e) 0.15, 90% interval 0.062 to 0.48. Missense variants: 115 observed, 210.67 expected, observed/expected ratio (o/e) 0.55, 90% interval 0.47 to 0.64. Synonymous variants: 78 observed, 87.02 expected, observed/expected ratio (o/e) 0.9, 90% interval 0.75 to 1.08.